MYO9B (myosin IXB)
Description:
Myosins are actin-based motor molecules with ATPase activity. Unconventional myosins serve in intracellular movements. Binds actin with high affinity both in the absence and presence of ATP and its mechanochemical activity is inhibited by calcium ions. Also acts as a GTPase activator for RHOA. Plays a role in the regulation of cell migration via its role as RHOA GTPase activator. This is regulated by its interaction with the SLIT2 receptor ROBO1; interaction with ROBO1 impairs interaction with RHOA and subsequent activation of RHOA GTPase activity, and thereby leads to increased levels of active, GTP-bound RHOA.
Synonyms: MYR5; CELIAC4
Tractability: Small molecule: a structure with a bound ligand is known. PROTAC: ubiquitination databases record sites on it; its protein half-life has been measured.
Gene: Protein-coding gene on chromosome 19 (17,075,728 to 17,214,537, forward strand). Ensembl gene ENSG00000099331.
Subcellular location: Cytoplasm, cell cortex; Cytoplasm, perinuclear region; Cytoplasm, cytoskeleton
Subcellular location (Human Protein Atlas): Cytosol
Pathways (Reactome):
Signal Transduction: CDC42 GTPase cycle; RAC1 GTPase cycle; RHOA GTPase cycle; RHOB GTPase cycle; RHOC GTPase cycle; RHOF GTPase cycle
Developmental Biology: SLIT2:ROBO1 increases RHOA activity
Disease: FCGR3A-mediated phagocytosis
Immune System: Regulation of actin dynamics for phagocytic cup formation
Gene Ontology:
Molecular function: actin binding; ADP binding; ATP binding; calmodulin binding; GTPase activator activity; microfilament motor activity; protein binding; protein homodimerization activity; Roundabout binding; small GTPase binding; actin filament binding; ATP hydrolysis activity; cytoskeletal motor activity
Biological process: actin filament-based movement; ARF protein signal transduction; regulation of Rho protein signal transduction; Roundabout signaling pathway; lamellipodium morphogenesis; regulation of small GTPase mediated signal transduction; Rho protein signal transduction; intracellular signal transduction; signal transduction
Cellular component: actin filament; cell cortex; cytoplasm; cytosol; membrane; perinuclear region of cytoplasm; postsynaptic actin cytoskeleton; actin cytoskeleton; lamellipodium; ruffle; cytoskeleton; myosin complex
Genetic constraint (gnomAD): Loss-of-function variants: 69 observed, 195.98 expected, observed/expected ratio (o/e) 0.35, 90% interval 0.29 to 0.43. The upper end of that interval is the gene's LOEUF score, 0.43, which puts it in group 1 of 6, group 1 being the genes least tolerant of losing a copy. Missense variants: 2,237 observed, 2,781.4 expected, observed/expected ratio (o/e) 0.8, 90% interval 0.78 to 0.83. Synonymous variants: 1,180 observed, 1,164.9 expected, observed/expected ratio (o/e) 1.01, 90% interval 0.96 to 1.06.
Homologues: Orthologues: dog MYO9B (88% identical), chimpanzee MYO9B (88% identical), rat Myo9b (83% identical), mouse Myo9b (83% identical), pig MYO9B (81% identical), guinea pig MYO9B (73% identical), rabbit MYO9B (63% identical), tropical clawed frog myo9b (60% identical), zebrafish MYO9B (52% identical). Paralogues in human: MYO9A (44% identical), MYH4 (20% identical), MYH6 (20% identical), MYH3 (20% identical), MYH8 (20% identical), MYH2 (20% identical), MYH7 (20% identical), MYH7B (20% identical), MYH1 (20% identical), MYH10 (19% identical), MYH13 (19% identical), MYH11 (19% identical), and 32 more.